TRAP1 (TNF receptor associated protein 1)
Diseases named in the same sentence as TRAP1 in open-access papers (continued):
Sharing a sentence is not in itself a finding about the gene and the disease.
systemic lupus erythematosus (1 paper, 2021). An autoimmune multi-organ disease typically associated with vasculopathy and autoantibody production. "Finally, we also report that some lupus-associated cytokines down-regulate Trap1 expression." (PMID 33746957, 2021). "Importantly, we also show that cytokines involved in lupus pathogenesis down-regulate Trap1 expression in splenocytes." (PMID 33746957, 2021). "More importantly, we could show that both IFN-γ and IL-6, two cytokines involved in lupus pathogenesis, significantly down-regulated Trap1 expression in spleen cells after in vitro culture, whereas no change was observed with IFN-α or IL-17A." (PMID 33746957, 2021). "Finally, we demonstrate that lupus cytokines down-regulate Trap1 expression." (PMID 33746957, 2021). "The fact that IFN-γ and IL-6 significantly down-regulated Trap1 in vitro suggests that those cytokines or other lupus-associated cytokines may similarly influence Trap1 expression in patients, potentially not exclusively in the spleen." (PMID 33746957, 2021). "The DNase1/Trap1-KO mice used in the present study do not develop lupus on the pure C57BL/6 genetic background, but develop the disease on the mixed 129 × C57BL/6 F2 genetic background, indicating that other genetic factors contribute to lupus." (PMID 33746957, 2021).
ulcers (1 paper, 2023). "ATF6B and TRAP1 are significantly abundant during the presence of ulcers when compared to the lesion-free groups." (PMID 37170213, 2023). "This, accompanied by the high abundance of amyloid-beta precursor protein (APP), apolipoprotein E (APOE), MADD (MAP kinase-activating death domain protein), ATF6B, ERN1 and TRAP1 in the presence of ulcers, shows that, along with cell death, the epithelial health maintenance response is strong." (PMID 37170213, 2023).
Ureteral obstruction (1 paper, 2021). Obstruction of the flow of urine through the ureter. "Interestingly, TRAP1 was shown to ameliorate renal tubulointerstitial fibrosis in mice with unilateral ureteral obstruction by protecting renal tubular epithelial cell mitochondria." (PMID 34795664, 2021).
cancer (127 papers, 2008 to 2025). A tumor composed of atypical neoplastic, often pleomorphic cells that invade other tissues. "Overall, our results point out the complex role of TRAP1 in cancer biology, showing that TRAP1 mutations have differential effects and revealing no direct correlation between its ATPase activity and functional effects." (PMID 40074754, 2025). "RESULTS: We found that TRAP1 significantly predicts cancer prognosis and is closely linked to immune and metabolic tumor characteristics." (PMID 41422190, 2025). "PURPOSE: Tumor necrosis factor receptor-associated protein 1 (TRAP1) is essential for carcinogenesis and the advancement of cancer, making it a promising therapeutic target in oncology." (PMID 41422190, 2025). "Further, TRAP1 degradation significantly reduces cancer cell’s ability to evade apoptosis associated with the regulation of the PI3K/Akt pathway, making them more susceptible to stress-induced cell death." (PMID 41322190, 2025). "The expression of TRAP1 in pan‐cancer was shown to be substantially inversely linked with that of HIGD1A and EFHD1, and positively correlated with that of PPARGC1A, according to a correlation study of 5 MRGs." (PMID 37903487, 2024). "In this complex scenario of molecular processes underlying pro-neoplastic mitochondrial adaptations, TRAP1 has been identified as one of the main regulators of mitochondrial bioenergetics of cancer cells." (PMID 39210159, 2024). "Overexpression of TRAP1 in cancer associated fibroblasts (CAFs) increases basal oxygen consumption rate (OCR) and ATP production." (PMID 38098505, 2023). "Five hypermethylated regions were in genes previously associated with cancer (TRAP1, SLC38A3, CHRM1, EDN2, and PROX1), while six hypomethylated regions were in genes previously associated with cancer (NUMBL, ALDH1B1, FTCD, FASTKD2, FAM96A, and ARHGAP15)." (PMID 36474183, 2022). "While these studies identify TRAP1 as cytoprotective in mitochondrial-associated neuropathologies, other studies have highlighted a potential pro-neoplastic role of TRAP1 in cancer, where it can also display cytoprotective and other pro-tumorigenic activities." (PMID 35883436, 2022). "Succinate-dependent HIF1α stabilization and activation promotes a well-established glycolytic transcriptional program, demonstrating yet another function of TRAP1 in the regulation of cancer-associated metabolic dysregulation." (PMID 35740911, 2022). "The tumor necrosis factor receptor-associated protein 1 (TRAP1) is a new therapeutic target in cancer." (PMID 33921908, 2021). "Silencing TRAP1 is associated with increase in capacity of CP in cancer elimination by enhancing ROS levels and mediating mitochondrial dysfunction." (PMID 33921908, 2021). "And TRAP1 was described to be involved in energetic metabolism in various cancer cells and was often associated with treatment resistance, but the exact role of which remains controversial." (PMID 33145341, 2020). "TRAP1 expression levels are also linked to tumour progression so it is a mitochondria chaperone protein stated to be a target for cancer treatment." (PMID 33488170, 2020). "In the context of cancer cells, overexpression of TRAP1 and silencing were shown to cause sudden growth inhibition and apoptosis." (PMID 33488170, 2020). "The high expression of TRAP-1 in cancer has been implicated in the inhibition of mitochondrial apoptosis, suppression of ROS production and acquisition of resistance to standard chemotherapeutics." (PMID 32585842, 2020). "The protein expression of the mitochondrial Hsp90 homologue, Tumor Necrosis Factor Receptor-associated Protein 1 (TRAP1), is increased in cancer cells." (PMID 31181660, 2019). "We show here that SDOS interacts with another important cancer-linked protein, the chaperone TRAP1, associates with actively translating polyribosomes and represses translation." (PMID 30260431, 2018).
cancer (continued). "Tumor Necrosis Factor Receptor-Associated Protein 1 (TRAP1) is a molecular chaperone involved in the regulation of energetic metabolism in cancer cells." (PMID 29621137, 2018). "Many of the associated proteins and cellular processes are relevant to cancer, and there is ample pharmacological and genetic evidence to support the idea that Hsp90a/βand Trap1 are required for tumorigenesis." (PMID 28407697, 2017). "G-TPP targets mitochondrial-localized members of the HSP90 family including TNF receptor-associated protein-1 (TRAP1) and was developed to treat cancer cells where cytosolic HSP90s are abundant inside mitochondria." (PMID 29290944, 2017). "Mitochondrial Hsp90 chaperone tumor necrosis factor receptor-associated protein 1 (TRAP1; also termed as Hsp75) is abnormally expressed in many cancers; it is also suggested to be a potential therapeutic target for cancer." (PMID 26517089, 2015). "Tumor necrosis factor receptor-associated protein 1 (TRAP1) is abnormally expressed in many cancers." (PMID 26517089, 2015). "However, it is important to underline that TRAP1 regulation of cancer bioenergetics is a multifaceted and complex process, based on the interaction of several signalling networks and that still deserves to be studied at multiple levels." (PMID 39210159, 2024). "Additionally, A recently published article reveals the mechanism of TRAP1-associated cancer treatment with CVM-1118 (foslinanib), a phosphoric ester compound selected from 2phenyl-4-quinolone derivatives." (PMID 38098505, 2023). "This suggests CVM-1118 may have the potential to treat cancer patients carrying STK11- or NF2-deficient mutation–via targeting TRAP1 and inhibiting the activation of mTOR/AKT signaling pathways." (PMID 37351538, 2023). "Importantly, this study revealed that the expression of HSPD1 and TRAP1, both potential targets for cancer drugs, is linked to sensitivity to certain drug categories in specific tumor types." (PMID 37508418, 2023). "Cancer-associated increases in TRAP1 expression suggest a role for TRAP1 in oncogenesis." (PMID 35740911, 2022). "Comparing HCC in the choline deficient model and choline supplemented model, significant methylation differences were seen in 11 genes previously associated with cancer (hypermethylation of TRAP1, SLC38A3, CHRM1, EDN2, and PROX1; hypomethylation of ALDH1B1, FTCD, FASTKD2, FAM96A, and ARHGAP15)." (PMID 36474183, 2022). "Increased expression of TRAP1 is linked to multiple mitochondrial adaptations of cancer cells." (PMID 29290944, 2017). "Cell motility is an important determinant of cancer invasive potential: therefore, we asked whether TRAP1 expression is linked to tumor progression in OC patients." (PMID 27977010, 2016). "Hsp90 and its mitochondrial homolog, tumor necrosis factor receptor-associated protein 1 (TRAP1), are abundant in the mitochondria of many cancer cells, and their regulation, client proteins, and cellular functions are quite different from the cytoplasmic Hsp90 pool." (PMID 24924916, 2014). "In addition, from the identified pharmacogenomic biomarkers of CVM-1118, treating cancer patients carrying specific mutations that activate signaling pathways downstream of TRAP1, such as mTOR and AKT, is expected to have a greater drug response that can be further tested in future clinical trials." (PMID 37351538, 2023). "While TRAP1’s biochemical functions have been extensively studied in the context of cancer and neurodegenerative diseases, its roles in vertebrate development remain largely unexplored." (PMID 40098710, 2025). "We observed that the presence of Mφ/M2 macrophages induced cancer cell migration, and this was maximally upregulated by TRAP1-expressing macrophages exposed to MPNST-CM." (PMID 40877908, 2025). "CONCLUSION: In summary, this study reveals the critical clinical significance of TRAP1 across multiple cancer types through a pan-cancer analysis." (PMID 41422190, 2025).
cancer (continued). "During nutrient deprivation, TRAP1 enhances glutamine metabolism to meet elevated energy demands, thereby supporting cancer cell survival and proliferation." (PMID 41226319, 2025). "Nevertheless, comprehensive bioinformatic analyses of TRAP1 across diverse cancer types are limited." (PMID 41422190, 2025). "Elevated expression of TRAP1 has been reported in various cancers, including hepatocellular carcinoma, breast cancer, glioblastoma, small-cell lung cancer, renal, prostate, ovarian, pancreatic, and colorectal cancers, and esophageal carcinomas." (PMID 41226319, 2025). "This study provides novel insights into the developmental functions of TRAP1 in Xenopus embryos, expanding our understanding of this vital chaperone beyond its well-established roles in cancer and neurodegenerative diseases." (PMID 40098710, 2025). "DN401, another TRAP1-selective inhibitor, also showed preferential binding and potent antiproliferative effects in cancer cells." (PMID 41226319, 2025). "Collectively, these findings indicate that both HDCA and GTE exert anticancer effects through inhibition of mitochondrial and cytosolic heat shock proteins, positioning TRAP1 as a promising therapeutic target for cancer treatment." (PMID 41226319, 2025). "The mitochondrial chaperone TRAP1 is a key regulator of cellular homeostasis and its activity has important implications in neurodegeneration, ischemia and cancer." (PMID 40074754, 2025). "We observe that expression of the molecular chaperone TRAP1, a master regulator of mitochondrial metabolic circuitries in different cancer cell types, is mandatory for skewing the macrophage phenotype toward a M2-like, pro-neoplastic one." (PMID 40877908, 2025). "We then extended our study to mouse malignant peripheral nerve sheath tumor (sMPNST) cells, as we previously demonstrated that TRAP1 plays a role in driving the tumorigenic properties of this cancer type." (PMID 40424720, 2025). "Herein, we analyzed TRAP1 across all cancer types, focusing on its expression in relation to prognosis, immune infiltration, and the mammalian target of rapamycin and receptor tyrosine kinase signaling pathways." (PMID 41422190, 2025). "The biochemical function of TRAP1 is at the center of cancer metabolism, and the TRAP1 inhibitor was extensively examined and is currently used by many researchers." (PMID 40098710, 2025). "By using a Boyden chamber assay, we found that DMS markedly increased the induction of MPNST cell motility by TRAP1 KO macrophages, making it reach the same level observed when cancer cells were co-cultured with TRAP1 WT macrophages." (PMID 40877908, 2025). "The ability of TRAP1-expressing macrophages to sustain cancer cell migration after exposure to MPNST-CM was also confirmed using media conditioned by two additional MPNST cell models." (PMID 40877908, 2025). "As expected, a significant upregulation of TRAP1 expression was observed in cancer tissues (|Log2FC| cutoff = 1; p-value cutoff = 0.01), confirming our previous observation obtained using TNMplot database." (PMID 39210159, 2024). "Studies in cancer have shown that TRAP1 is a heat shock protein (HSP) that regulates the metabolic shift between glycolysis and oxidative phosphorylation (OXPHOS)." (PMID 39224595, 2024). "Trap1 was primarily studied in cancer cells, facilitating tumor progression through modulation of cell metabolism." (PMID 39333440, 2024). "Intracellular and extracellular HSP90 family members (HSP90α, HSP90β, GRP94 and TRAP1) promote cancer by sustaining various hallmarks of cancer, including cell death resistance, replicative immortality, tumor immunity, angiogenesis, invasion and metastasis." (PMID 39148727, 2024). "Considering all these data, it seems obvious that in most cases, TRAP-1 expression is higher in cancer cells than in normal tissues." (PMID 37345199, 2023). "TRAP1 improve cancer cells’ resistance to various stresses including anticancer therapies by upregulating cell death threshold." (PMID 38098505, 2023).
cancer (continued). "Although the function of TRAP1 is controversial, the majority of the literature suggests that TRAP1 is overexpressed in many cancers and regulates metabolic transformation during tumourigenesis, and that TRAP1 attenuation is detrimental to tumor cell survival." (PMID 38098505, 2023). "In agreement with Hanahan and Weinberg55, who proposed the hallmarks of cancer, our findings integrate that TRAP-1 modulates cellular energy metabolism and probably links mitochondria-independent energy metabolism with mitochondria-dependent energy metabolism." (PMID 37165028, 2023). "Compared to other Hsp90 inhibitors, many new small molecule drugs that target TRAP1 or mitochondria show better performance in controlling cancer cells and reducing cellular toxicity." (PMID 38098505, 2023). "Our findings suggest that TRAP-1 manipulates metabolic pathways and thus favors metabolic rewiring in cancer cells." (PMID 37165028, 2023). "It has been shown that MitoQ, a mitochondria-targeted antioxidant, effectively inhibits the function of Hsp90 by reacting with TRAP1, thus exhibiting powerful anti-cancer activity." (PMID 36765624, 2023). "It is known that overexpression of TRAP1 exerts its protective function in cancer cells by inhibiting the activation of CypD." (PMID 37351538, 2023). "The downregulation or depletion of TRAP1 in cancer cells impairs ATP generation and mitochondrial membrane potential, disturbs mitochondrial function, reduce proliferation, and has variable effects on apoptosis." (PMID 38098505, 2023). "Curiously, however, TRAP1 is overexpressed in many cancers, allowing for the possibility that TRAP1-SNO is context-specific and perhaps also under temporal regulation." (PMID 35740911, 2022). "TRAP1 upregulation facilitates the growth and progression of many cancers by promoting glycolytic metabolism and antagonizing the mitochondrial permeability transition that precedes multiple cell death pathways." (PMID 35740911, 2022). "Here, we will discuss the consequence of TRAP1 deregulation in cancer and the impact of post-translational modification on the known functions of TRAP1." (PMID 35740911, 2022). "TRAP1 attenuation induces apoptosis in cellular models of cancer, identifying TRAP1 as a potential therapeutic target in cancer." (PMID 35740911, 2022). "One of the mechanisms by which TRAP-1 promotes cancer growth is through binding to SDH thereby inhibiting SDH catalytic activities and disrupting electron transfer, leading to succinate and ROS accumulation." (PMID 36344992, 2022). "TRAP1 control of cellular metabolic flux and mitochondrial apoptosis outlined herein identifies TRAP1 inhibition as a potential anti-cancer therapeutic target." (PMID 35740911, 2022). "In the present study, shRNA knockdown of TRAP1 was found to reduce the mitochondrial membrane potential in motor neurons; these findings are in agreement with studies in cancer cell lines." (PMID 35163711, 2022). "Here, we will discuss recent advances in understanding the mechanisms of TRAP1 regulation, the impact of this regulation on TRAP1 function and downstream cellular processes, and the role of TRAP1 in cancer." (PMID 35740911, 2022). "Long lines of experimental evidence suggest that TRAP1 is involved in tumor metabolism and cytoprotection of cancer cells." (PMID 35127545, 2022). "Recent studies revealed that TRAP1 silencing results in cell cycle G2M phase progression in cancer cells." (PMID 35765067, 2022). "The regulation of cancer cell metabolism by TRAP1 appears to have contextual effects on cancer onset and progression, thus favoring the oncogenic phenotype in glycolytic tumors, while being negatively selected in tumors mostly relying on oxidative metabolism." (PMID 36510251, 2022). "A recently-identified actor in this regard is the molecular chaperone TRAP1, that is considered an oncogene in several cancers for its high expression but an oncosuppressor in others with predominant oxidative metabolism." (PMID 36510251, 2022).